KLF4 (KLF transcription factor 4)
Diseases named in the same sentence as KLF4 in open-access papers (continued):
Sharing a sentence is not in itself a finding about the gene and the disease.
cancer (continued). "We also detected significantly high expression of OCT4, SOX2, KLF4 and BMI1 in the HPV-negative OPC CSCs as compared to the cancer cells, while CD133 expression was not different in the CSCs and the cancer cells." (PMID 34359786, 2021). "Although The Cancer Genome Atlas includes reverse phase protein array (RPPA) data, KLF4 protein is not included within this array, impeding the ability to assess this association." (PMID 32552913, 2020). "In cancer cell lines, CaMKIIγ was positively correlated with OCT4 and NANOG expression, but was not correlated with MYC or KLF4." (PMID 25965829, 2015). "Here, we report that the antifungal agent ciclopirox olamine (CPX), a potential candidate for drug repurposing in cancer treatment, is able to reprogram gastric non-CSCs into cancer stem-like cells via activation of SOX2 expression and increased expression of C-MYC, HIF-1α, KLF4, and HMGA1." (PMID 37686684, 2023). "The expression of previously-reported candidate marker genes, such as CD133, CD44 and ABCG2, which are argued to be related to cancer stem cells, and the transduced genes OCT3/4, SOX2 and KLF4 were not significantly different among the parental A549, OSK-A549-Colony and OSK-A549-SN cells." (PMID 28951614, 2017). "For KLF4, increased gene expression was observed in both 97L and HCT116 cells despite the fact that the CpG island methylation pattern was indistinguishable between normal and cancer cells." (PMID 24023739, 2013). "KLF4 protein is predominantly expressed in cytoplasm but not in nucleus of CRC-derived cells, suggesting that impaired nuclear translocation of KLF4 contributes to cancer formation." (PMID 20119532, 2009). "Importantly, we detected an increased membranous expression and colocalization of β-CAT, E-CAD and EpCAM in the KLF4-overexpressing EpCAM−/CD133− non-stem cells, suggesting that this complex might be required for the cancer stem cell phenotype." (PMID 32408542, 2020).
infection (76 papers, 2009 to 2026). The state of being infected such as from the introduction of a foreign agent such as serum, vaccine, antigenic substance or organism. "This decline in KLF4-driven rhythmicity probably contributes to the age-associated vulnerability to infections and inflammatory diseases in older individuals." (PMID 40313940, 2025). "The KLF4 master regulator has been implicated in this transcriptional reprogramming of myeloid cells to induce trained immunity in response to infection." (PMID 40552304, 2025). "The loss of KLF4 disrupts these processes, compromising immune responses and increasing susceptibility to infection." (PMID 40831570, 2025). "(ii) Transient induction of KLF4 expression or molecular off switch as prolonged hyperinflammation exceeding the initial phase of infection likely causes deleterious collateral damage to host lung tissue." (PMID 34589087, 2021). "The repression in KLF4 levels associated with transfection of a miR-26a mimic prior to infection, occurred even in the presence of MG132 supporting the notion that miR-26a mediates its effects in a proteasome-independent manner." (PMID 28558034, 2017). "A post-transcriptional mechanism of upregulation of KLF4 linked to the downregulation of cellular miR-145 has been reported during infection of keratinocytes with human papillomavirus." (PMID 28558034, 2017). "The repression of miR-26a during infection is associated with enhanced KLF4 which skews the balance between arginase and iNOS towards the former." (PMID 28558034, 2017). "We have linked the downregulation of miR-26a during infection with the translational upregulation of KLF4." (PMID 28558034, 2017). "We used Rb-NSCs isolated from the Oct4-EGFP transgenic fetuses to tentatively generate Rb-iPSCs through the infection of lentiviral vectors that encode four human transcription factors (Oct4, Sox2, Klf4 and c-Myc)." (PMID 25360692, 2014). "The resulting increased susceptibility to infections, such as Escherichia coli, in myeloid-specific conditional KLF4-deficient mice is, however, accompanied by a reduced risk of excessive systemic inflammation and septic shock in response to Escherichia coli infection in these animals." (PMID 40313940, 2025). "In pneumococcal pneumonia, KLF4 in myeloid cells is essential for an effective early immune response as its deficiency leads to reduced pro-inflammatory cytokine levels, impaired bacterial clearance, and increased disease severity in the early course of infection." (PMID 40313940, 2025). "Therefore, blood-derived PMNs and bone marrow-derived macrophages (BMMs) were isolated from myeloid KLF4 knockout (mKLF4 KO) and KLF4 wildtype (mKLF4 WT) mice and stimulated for 6 hours with capsule-deficient R6x pneumococci (multiplicity of infection (MOI) 1)." (PMID 34589087, 2021). "KLF4 downregulation significantly reduces infection-induced preterm birth rates and adverse pregnancy outcomes, suggesting that KLF4 is a critical therapeutic target for preterm birth." (PMID 41694684, 2026). "We observed a pronounced reduction in the number of tumorspheres in the Ad-VP3 group, and a time-dependent decrease in the expression of the stemness markers ALDH1A1, KLF4, and Sox2 at 48 and 72 h post-infection." (PMID 41472305, 2025). "Krüppel-like factor 4 (KLF4), a multi-functional transcription factor, is known to regulate pathogenic infections; however, its specific roles in PEDV infection remain largely undefined." (PMID 40867674, 2025). "In this study, we observed increased PEDV infection in KLF4 knockout cells but decreased infection in KLF4 overexpression cells, indicating an important role for KLF4 in the cellular response to PEDV infection." (PMID 40867674, 2025). "This review summarizes current knowledge on the function of KLF4 in phagocytes during infections, highlighting its regulatory mechanisms, context-dependent roles, and its impact on immune activation and resolution." (PMID 40313940, 2025).
infection (continued). "Infection of primary rat VSMCs with lentiviral shRNA targeting KLF4 (sh-KLF4) efficiently reduced KLF4 protein expression." (PMID 41307849, 2025). "The transcription factor KLF4 was also significantly induced post-infection and also at least partially transcriptionally dependent on EGR1." (PMID 35746681, 2022). "Reprogramming was performed using a stoichiometric ratio-based infection of equivalent amounts of retroviruses encoding a POU5 protein (mOct4, X91 or X25) and the three factors KLF4, SOX2, and c-MYC." (PMID 36130934, 2022). "The transduction of CagA or infection with H. pylori downregulates KLF4 expression by inducing CXCL8 expression, and low KLF4 expression further upregulates CXCL8 expression." (PMID 35967444, 2022). "Infection with ZIKV resulted in a significant increase in KLF4 expression as well as a dramatic decrease in FOS transcription." (PMID 35746681, 2022). "Myeloid KLF4 KO mice showed earlier and significant stronger symptoms of infection compared to KLF4 WT mice." (PMID 34589087, 2021). "Myeloid KLF4 KO mice showed a higher alveolar-capillary permeability 24 hours post infection compared to KLF4 WT mice." (PMID 34589087, 2021). "Myeloid KLF4 KO mice showed a significant higher bacterial load in lungs and blood and tended to have a higher bacterial load in the spleen 24 hours post infection compared to KLF4 WT mice." (PMID 34589087, 2021). "Semiquantitative scoring of immunohistochemistry staining of lung sections with a polyclonal antibody against S. pneumoniae confirmed the higher amount of bacteria in the lungs of myeloid KLF4 KO mice 24 hours after infection." (PMID 34589087, 2021). "Myeloid KLF4 KO mice showed a marked drop of body temperature between day 2.5 to 3 post infection compared to KLF4 WT mice." (PMID 34589087, 2021). "We utilized KLF4 overexpression by adenovirus (Ad)-KLF4 infection to further delineate the role of KLF4 in regulating SRA expression." (PMID 31938053, 2020). "Two days after infection, protein was harvested and expression of KLF4 and its previously reported target, E-cadherin (CDH1), were confirmed." (PMID 32552913, 2020). "Consistent with our qRT-PCR analysis, infection of HDFn cells with ΔNp73β in combination with KLF4 + ΔNp63α led to increased expression of KRT14, KRT5, FLG, and SFN as compared to KLF4 + ΔNp63α with control or control alone." (PMID 31216312, 2019). "We transfected urine cells with SeV encoding OCT3/4, SOX2, KLF4, and c-MYC and found that human embryonic stem cell-like colonies first appeared 5 to 8 days after infection." (PMID 31412925, 2019). "The results showed that the expression of KLF4 approximately reduced by 4- and 7-folds after 6 and 10 weeks of infection with S. japonicum, respectively, compared to the age-matched uninfected group." (PMID 31886304, 2019). "Co-expression of ΔNp73 isoforms with KLF4 + ΔNp63α led to increased expression of keratinocyte genes compared to KLF4 + ΔNp63α with empty vector control infections." (PMID 31216312, 2019). "Klf4 shRNA is stablyexpressed in ES cells through lentiviral infection, andknockdown of Klf4 induces ES cell differentiation." (PMID 29105400, 2018). "The role of the miR-26a/KLF4 axis in regulating autophagy was further evaluated by silencing Klf4 prior to infection." (PMID 28558034, 2017). "Considering that KLF4 levels remained well above basal levels even at 24 h post-infection, we narrowed down on miR-26a." (PMID 28558034, 2017). "When cells were transfected with a miR-26a mimic along with a plasmid expressing KLF4 prior to infection, the levels of Mcl-1 increased compared to cells transfected with miR-26a mimic alone." (PMID 28558034, 2017). "Overexpression of KLF4 was observed in AECs upon infection of AdKLF4 and Ad tetracycline transactivator (AdtTA)." (PMID 29158503, 2017). "In order to elucidate the role of NO in the KLF4- or miR-26a-dependent control of bacterial CFUs, we transfected cells with Klf4 siRNA prior to infection." (PMID 28558034, 2017).
infection (continued). "All iPSCs were generated through the infection of fibroblasts with retroviruses encoding OCT4, SOX2, KLF4 and C-MYC, displaying typical features of human pluripotent stem cells." (PMID 27926491, 2017). "It is interesting to note that the best protocol of infection is achieved by the initial addition of Oct4 and Klf4 together, where Oct4 directly induces SNAI2 and Klf4 induces E-Cadherin, but not by Oct4 on its own." (PMID 26771648, 2016). "The withdrawal of either Klf4 or c-Myc decreased the percentage of Oil Red O-positive cells 9 days after infection, compared with that observed when these factors were present." (PMID 27077806, 2016). "In a similar manner, it was not possible to generate stable cell lines of HFKs following infection with lentiviruses expressing KLF4 shRNAs, whereas both HFK-31gen and HFK-16gen cells readily formed lines with stable KLF4 depletion." (PMID 27386862, 2016). "KLF4 levels were reduced following infection with pooled shKLF4 lentiviruses compared to infection with mock and shGFP controls." (PMID 27386862, 2016). "Viral c-Myc was transiently upregulated along with Klf4 2 days after infection but decreased after the cells were cultured for 2 weeks." (PMID 25497456, 2015). "Infection with Ad-Klf4 resulted in morphological changes, down-regulation of mesenchymal markers, and re-expression of both epithelial and pancreatic cell markers including insulin and transcription factors specific to β-cells." (PMID 26457418, 2015). "First we found that KLF4 expression was significantly recovered after infection of lentivirus vector containing KLF4 coding sequence (without 3′UTR) other than control." (PMID 26172296, 2015). "We generated these partial iPSCs by infection of MEFs with retroviruses carrying either Oct3/4, Sox2, Klf4, or rtTA genes together with a virus carrying both c-Myc and DsRed cDNAs." (PMID 24386274, 2013). "Lentiviral vectors encoding human OCT4, SOX2, KLF4 and c-MYC, at an approximate multiplicity of infection of 5 each, transduced early passage human keratinocytes (HK cells) derived from 56 to 78 year-old individuals with or without T2D." (PMID 22308265, 2012). "Experimental results outlined here suggest mcMyc regulates the initial (<5 days) suppression of Thy1 in MEF, followed by a cooperative mechanism driven by mcMyc/Klf4 from 5–9 days after infection." (PMID 22619682, 2012). "At 14 days, pretreatment of MEF with exogenous Klf4 + 100 nM pTAT-mcMyc before Oct4/Sox2 infection at day 0, significantly repressed Thy1 than cells infected with Oct4/Sox2 alone." (PMID 22619682, 2012). "During infection, LPS-induced KLF4 expression can promote IL-10 release, particularly in the early course of infection, while later it may contribute to the release of high mobility group box 1 protein (HMGB1), a rather pro-inflammatory mediator." (PMID 40313940, 2025). "In summary, productive infection was stimulated the most by Sp3, KLF4, GR, and DEX treatment." (PMID 40006984, 2025). "Infection with Mycobacterium tuberculosis strongly induces KLF4 expression, leading to M2 polarization with decreased expression of antibacterial effectors such as iNOS and impaired trafficking of Mycobacterium tuberculosis to lysosomes, thereby promoting bacterial survival." (PMID 40313940, 2025). "Importantly, a majority of these DEGs showed opposite expression changes when comparing PEDV-infected wild-type cells to PEDV-infected KLF4 knockout cells, underscoring the regulatory role of KLF4 during infection." (PMID 40867674, 2025). "They demonstrated that during infection with Pseudomonas aeruginosa, tissue-resident alveolar macrophages undergo KLF4-mediated transcriptional reprogramming, which confers a pro-efferocytosis phenotype (the phagocytic removal of dead or apoptotic cells) by upregulating MERTK." (PMID 40552304, 2025).
infection (continued). "In vivo cDCs with conditional deletion of KLF4 demonstrated impaired Th2 cell response to infection by Schistosoma mansoni and house dust mites, although Th1/Th17 cell responses were unaffected in response to other infections." (PMID 40831570, 2025). "In cerebral malaria, infection with Plasmodium berghei ANKA leads to platelet-dependent upregulation of KLF4 in macrophages, resulting in increased production of pro-inflammatory cytokines such as IL-6, which probably worsens disease severity and the overall outcome." (PMID 40313940, 2025). "These genes included key components involved in TLR4 inflammatory responses to infection, such as KLF4, for which the context-specific eQTLs link differential enhancer activity and/or chromatin accessibility that were positively correlated with mRNA levels upon LPS treatments." (PMID 35751107, 2022). "Interestingly, two recent studies reported that Klf4 is robustly upregulated upon infection with pathogens like E. coli or Streptococcus pneumoniae." (PMID 34721415, 2021). "Post infection integrity of the alveolar-capillary barrier in myeloid KLF4 KO and KLF4 WT mice was assessed by determining the concentration of albumin in the bronchoalveolare lavage fluid (BALF) over that in plasma 24 hours after transnasal inoculation with PBS or 5x105 CFU NCTC 7978 pneumococci." (PMID 34589087, 2021). "Similarly, KLF4 was upregulated in HT-29 cells upon WT V. vulnificus infection but was downregulated in dTHP-1 cells upon infection with both WT and ΔrtxA1V. vulnificus." (PMID 32817457, 2020). "After 24 hours of infection, compared with the control group, the fluorescence intensity of the KLF4 group (green) was significantly reduced and the fluorescence intensity of the si-KLF4 group was significantly enhanced under the fluorescence microscope." (PMID 32674073, 2020). "Notably, the degree of KLF4 overexpression as a result of AdKLF4 infection in these cells was similar to the levels of KLF4 observed in MCF10A cells, indicating that the expression levels were within the endogenous range of non-transformed cells." (PMID 32552913, 2020). "We searched for an inverse relationship between KLF4 and miRNA expression during infection." (PMID 28558034, 2017). "Klf4 was downregulated and C/ebpbeta was upregulated in macrophages, 24 h post-infection." (PMID 28558034, 2017). "Intriguingly, the expression of the KLF4 protein was upregulated during infection." (PMID 28558034, 2017). "From our previously archived data, we searched for miRNAs which could potentially target KLF4 and which were also downregulated during infection." (PMID 28558034, 2017). "However, expression of the KLF4 protein was enhanced during infection, indicating uncoupling of transcriptional and translational regulation." (PMID 28558034, 2017). "Interestingly, preinfection with Klf4 (thus prerepressing Thy1), with subsequent Oct4/Sox2 infection, was equally effective at repressing Thy1 at 14 days than infecting cells concurrently with OSK (compare blue and orange lines)." (PMID 22619682, 2012). "We next tested whether a synchronized population could elevate the expression of reprogramming factors after OCT3/4, SOX2, C-MYC, and KLF4 infection." (PMID 22529890, 2012). "Moreover, we generated reprogrammable rats from riPSCs that were created by infection of three reprogramming factors (Oct3/4, Klf4, and Sox2) via an inducible lentiviral vector." (PMID 21789202, 2011). "We here show that infection with a lentiviral vector carrying three mouse reprogramming factors (Oct4, Klf4, and Sox2) and culture in the presence of two kinds of kinase inhibitors (MEK inhibitor and GSK3 inhibitor) permit efficient establishment and maintenance of riPSCs from REFs." (PMID 21789202, 2011). "To determine whether PF4 has a role in driving KLF4 expression during ECM we isolated spleens from infected WT and PF4−/− mice on day 4 post-infection and quantified KLF4 expression by qRT-PCR." (PMID 20454664, 2010).